CA9 (carbonic anhydrase 9)
Diseases named in the same sentence as CA9 in open-access papers (continued):
Sharing a sentence is not in itself a finding about the gene and the disease.
tumor (continued). "Studies have shown that the high expression of CA9 promotes viability and growth of tumor cells in melanoma, breast, and colorectal cancers, and enhances tumor invasion and migration by promoting extracellular matrix degradation." (PMID 32824856, 2020). "CA9 was highly expressed in tumor cells in all cases and was moderately expressed in normal tissue, confirming the Western blot results." (PMID 33276608, 2020). "It is known that carbonic anhydrase IX (CA9) is a hypoxia-regulated, transmembrane protein associated with neoplastic growth in a broad spectrum of human tumours." (PMID 32181755, 2020). "The almost exclusively tumor-specific CA9, whose gene is induced by the hypoxia-inducible factor-1α, is a transmembrane enzyme aimed at controlling intracellular pH changes that result from the accumulation of acidic metabolites under hypoxic conditions." (PMID 32781554, 2020). "It has been shown that CA9 enhances tumor invasion and migration by promoting extracellular matrix degradation through a pH-dependent mechanism." (PMID 32824856, 2020). "The analysis of the clinical features of the TSCC TCGA cohort showed that CA9 expression levels correlate with patients’ tumour grade." (PMID 32299152, 2020). "We observed high expression of NFKB2 and CA9 positivity significantly predicted the tumor recurrence in our cohort; p = 0.0004 and p = 0.02, respectably." (PMID 32839486, 2020). "Given the restricted presence in normal tissues and upregulation in solid tumors, CA9 has gained considerable interest as a novel tumor target." (PMID 33007872, 2020). "Previous studies demonstrated that CA9 formed a transport metabolon with AEs, NBCs, and monocarboxylate transporters (MCTs) to maintain pH homeostasis in tumor cells." (PMID 32824856, 2020). "This is an important path since CA9 has been found to be expressed by many solid tumors of different histotypes, and its activity has been correlated to tumor progression and growth." (PMID 32788634, 2020). "Such patients would, eventually, benefit from a combination of immunotherapy with pharmaceutical agents that neutralise extracellular tumour acidity, such as CA9 and bicarbonate transport inhibitors." (PMID 32066909, 2020). "Another disadvantage of CA9 as a theranostic target is that its presence in tumor tissues is induced by tissue hypoxia." (PMID 33007872, 2020). "In contrast, tumor cells showed a strong expression of CA9, which was further increased on the tumor exosomes." (PMID 33276608, 2020). "We measured mice survival and tumor growth rate after xenografts of human NB treated with cisplatin in the presence of MCM2/carbonic anhydrase 9 inhibitors (ciprofloxacin and acetazolamide)." (PMID 33153038, 2020). "Our results showed that areas of FABP5 staining overlapped with areas of CA9 staining, suggesting that hypoxic areas in these tumours strongly expressed FABP5." (PMID 32550890, 2020). "EVs were characterized using transmission electron microscopy, nanoparticle tracking analysis, and Western blotting using exosome and putative tumor markers (epithelial cell adhesion molecule (EpCAM), carbonic anhydrase 9 (CA9), CD70, CD147)." (PMID 33276608, 2020). "Silencing of CA9 in the EpCAM+/CAIXhigh TICs population resulted in failed tumor initiating activity in mice xenografts." (PMID 32707920, 2020). "For the male population, the presence of CA9 SNP rs2071676 AG + GG genotype was also correlated to a lower tumor stage (p = 0.037) and fewer lymph node invasion (p = 0.003) in those with EGFR wild type." (PMID 32365566, 2020). "In any case, CA9, appearing to be a marker of tumour aggressiveness by reflecting active hypoxia pathways, is also a marker of local immunosuppression and Treg accumulation." (PMID 32066909, 2020). "The transcription levels of CA9 in the tumours were significantly higher than those in normal tissues." (PMID 32299152, 2020).
tumor (continued). "The role of CA9 in the regulation of pH in the tumor microenvironment and induction of CA9 expression in response to tumor tissue hypoxia has been demonstrated." (PMID 33007872, 2020). "Our results indicated that CA9 high expression was related to TSCC patients’ poor outcome and that was mediated by oncogenes and tumour‐associated pathways." (PMID 32299152, 2020). "It has been previously postulated that extracellular CAs such as CA9 (upregulated in both tumor types), act to raise the extracellular pH favoring tumor cell growth, proliferation, and survival." (PMID 32293332, 2020). "The resulting tumour xenografts were subsequently analysed by immunohistochemistry using antibodies specific for ERO1α and CA9, and the localisation of the proteins was compared to the staining with pimonidazole." (PMID 31142270, 2019). "In an effort to identify the function of CA9 in tumor cells, we found that the hypoxia-related molecules CA9 and GLUT-1 were highly expressed in TC samples." (PMID 30863491, 2019). "Circulating tumour cells (CTCs) from MDA-MB-231 tumours respond differently to hypoxia than parental cells in the expression of specific hypoxia/HIF1-regulated genes like CA9." (PMID 31810330, 2019). "In RCC, hypoxic conditions stimulate the release of tumor cells-derived EVs that are enriched with carbonic anhydrase 9 (CAIX), an HIF induced gene that regulates the proliferation and migration of endothelial cells." (PMID 31013896, 2019). "The analysis revealed a strong expression of the tumor marker CA9 in LP derived cells only (p < 0.05) compared to those cells from RP and SC fat." (PMID 31640774, 2019). "On the other hand, a hypoxia gene expression signature that included VEGFA and CA9 was significantly higher in low resource tumours." (PMID 31648981, 2019). "Since tumour spheres simulate the actual tumour hypoxic microenvironment, we analysed the expression and localisation of ERO1α and CA9 in tumour spheres obtained from HCT116 and HeLa cells through sphere formation assays." (PMID 31142270, 2019). "The analysis revealed a strong expression of the tumor marker CA9 which was detected only in LP derived cells (p < 0.05) compared to those cells from RP and SC fat." (PMID 31640774, 2019). "CA9 is highly induced at hypoxic and acidic conditions and constitutes a major player in the regulation of tumor pH homeostasis by the reversible hydration of CO2 into HCO3− + H+." (PMID 30767150, 2019). "The CA9 mRNA level was also correlated with the mRNA expression of other HIF1 target genes in the investigated tumor samples such as glucose transporter 1 (Glut1≙ SLC2A1), glyceraldehyde-3-phosphate dehydrogenase (GAPDH), VEGFa and with miRNA-210 expression." (PMID 30654595, 2019). "HCT116 cells were transplanted into nude mice to compare the localisation of ERO1α and CA9 in in vivo tumours." (PMID 31142270, 2019). "Stem cell relative marker CD44, CD90, and CD105 and tumor marker CA9 and osteopontin (OPN) expression were quantified using RT-qPCR." (PMID 31640774, 2019). "The CA9 mRNA levels of 72 OSCC samples as well as of 24 tumor adjacent tissue samples were measured and normalized to the RNA polymerase II (RPII) mRNA level." (PMID 30654595, 2019). "Our immunohistochemical studies with ERO1α, CA9, and pimonidazole (an exogenous marker typically used to detect chronic hypoxia in tumour xenografts) indicated that the distribution of pimonidazole and ERO1α were very similar." (PMID 31142270, 2019). "CA9 expression was significantly associated with Masaoka stage, WHO classification, and recurrence-free survival after tumor resection (P = 0.005)." (PMID 30863491, 2019). "The expression and localisation of ERO1α and CA9 in tumour spheres during hypoxia were analysed by a tumour sphere formation assay." (PMID 31142270, 2019).
tumor (continued). "Patients with high levels of CA9 mRNA in the tumor tissue had a median overall survival of 11 months post-diagnosis compared to patients with low CA9 mRNA level who had a median overall survival of 42 months (Kaplan–Meier–analysis (p = 0.038))." (PMID 30654595, 2019). "Specifically, CA9 is considered a useful hypoxic and tumour marker and a “surrogate” of HIF-1α because its expression is induced by HIF1-α." (PMID 31142270, 2019). "Recently, it was shown, that CA9 ECD is increased in response to induction of apoptosis in tumor cells or by treatment with chemotherapeutic drugs presenting cell death as another source of CA9." (PMID 30011326, 2018). "Carbonic anhydrase 9 (CA9) is involved in hypoxic survival of tumor cells and mediates resistance to both adjuvant chemotherapy and endocrine therapy in BC." (PMID 29719590, 2018). "One important component of pH regulation is carbonic anhydrase IX (CA9) that exists both as a transmembrane protein and as a shed ectodomain circulating in the blood of tumor patients." (PMID 30338239, 2018). "Upregulation of CA9 in tumors is an effective adaptive response to hypoxia and increases the tumor cell survival." (PMID 30011326, 2018). "Carbonic anhydrase 9 (CAIX) staining confirmed that the normal epithelium was less hypoxic than adjacent tumour." (PMID 30467386, 2018). "Then, carbonic anhydrase-IX (CA-9), a biomarker that highly correlated with tumor hypoxia was used to stain the tumor hypoxic region." (PMID 29700283, 2018). "Pathology of tumors showed characteristic ELST morphology with immunoexpression of CK7, GFAP, S100, PAX-8, PAX-2, CA-9 in the tumor cells." (PMID 30340515, 2018). "Based on these results, we performed immunohistochemistry of GGT1 and CA9 for primary tumor and mLNs of the mouse model." (PMID 30542087, 2018). "We observed that CAIX expression in the CA9 tumours imposed an upper limit on tumour pHe, thus lowering the steady-state pH in their extracellular space." (PMID 30206370, 2018). "The extracellular domain (ECD) of CA9 can be released into the body fluids of (tumor) patients, where it is measured as serum CA9." (PMID 30011326, 2018). "CA9 expression is important for tumor cell growth, and CA9 functions by stabilizing intracellular pH to counteract the acidification that occurs in response to metabolic changes under hypoxic conditions." (PMID 30214007, 2018). "The results presented in this manuscript support a dual-targeting strategy with second-generation APE1/Ref-1 inhibitors and CA9 inhibitors resulting in enhanced inhibition of 3D PDAC tumor growth." (PMID 30214007, 2018). "APE1/Ref-1 redox activity and CA9 activity are important for tumor cell growth and survival, and CA9 functions as part of the pH regulatory cycle in hypoxic cells." (PMID 30214007, 2018). "APE1/Ref-1 redox inhibition significantly decreased the expression of CA9 protein in 3D tumor cultures in a concentration-dependent manner." (PMID 30214007, 2018). "Reduced levels of APE1/Ref-1 and/or CA9 significantly inhibited 3D tumor spheroid growth by ~50–80% (p < 0.001) as measured by fluorescence intensity and area." (PMID 30214007, 2018). "Among these genes, we focused on CA9, because previous studies have shown that CA9 promotes tumor cell migration and invasion in vitro by inhibiting the RHOA pathway, and is highly expressed in younger patients with cervical and hepatocellular malignancies." (PMID 30034621, 2018). "Dual-targeting of APE1/Ref-1 and CA9 in 3D spheroids demonstrated that this combination effectively kills PDAC tumor cells displaying drastically different levels of CA9." (PMID 30214007, 2018). "Given the role of CA9 in regulating tumor cell pH, which affects overall survival and cellular function, the findings elucidated here contribute to hypoxia signaling and pH regulation in PDAC cells with significant translational implications." (PMID 30214007, 2018).
tumor (continued). "Cells bathed in a more acidic milieu, such as CA9 tumour cells, are therefore expected to retain more lactate." (PMID 30206370, 2018). "The authors obtained higher levels of CA9 in tumours at lower stages compared with the more advanced stages." (PMID 29745265, 2018). "Compared to HT-1080 cells cultured under normoxic conditions, tumour xenografts showed a 5.6-, 3.9- and 4.2-fold increase in CA9, GLUT1 and MCT4 gene expression, respectively." (PMID 28635961, 2017). "We have shown that combined inhibition of VEGF and CA9 act at least additively and in some examples synergistically to reduce tumour growth." (PMID 27292261, 2017). "CA9 expression is induced in tumor cells under hypoxia and helps maintain a normal intracellular pH while facilitating an acidic extracellular pH4." (PMID 28667334, 2017). "Taken together, these in vivo data provide further support that miR-34a and CA9 have functions in regulating tumor growth and metastasis of HCC cells." (PMID 28667334, 2017). "CA9 has been at the forefront of therapeutic development due to its nearly exclusive tumor expression pattern and induction by hypoxia." (PMID 28055960, 2017). "In contrast, both HIF-1α and CA9 were clearly expressed in all of the pre-Bev initial and post-Bev recurrent tumors, suggesting that tumor oxygenation was improved with Bev treatment but returned to the original hypoxic condition in tumors refractory to Bev." (PMID 29262608, 2017). "To define the consequence of MMP-14 blockade within the TME, we examined markers of tumor vasculature (CD31), hypoxia (CA9), and a marker of anti-tumor M1 tumor-associated macrophages (TAMs; iNOS)." (PMID 28938563, 2017). "This gene disruption approach validates the importance of CA9 in both in vitro and in vivo tumor progression, particularly in hypoxia." (PMID 28055960, 2017). "CA9-ko resulted in the most substantial tumor growth reduction (∼90%) while NHE1/CA9-dko tumors grew at a surprisingly greater rate than both NHE1-ko and CA9-ko tumors." (PMID 28055960, 2017). "NHE1-ko significantly reduced tumor cell proliferation both in normoxia and hypoxia while CA9-ko dramatically reduced growth in hypoxic conditions." (PMID 28055960, 2017). "Overexpression of miR-34a led to a significant decrease in the primary tumor size in the liver and CA9 co-overexpression reversed this effect (p < 0.01, Student’s t-test)." (PMID 28667334, 2017). "Contributions of CO2/HCO3- balance to tumor pHi and pHe surged to the forefront of the literature following the discovery that the extracellular facing carbonic anhydrase 9 (CA9) is robustly regulated by hypoxia." (PMID 28055960, 2017). "CA9 also plays a role in the metastatic capacity of tumor cells due to its catalytic generation of H+ in the extracellular space." (PMID 28055960, 2017). "Studies involving CA9 knockdown from our group and others established that CA9 contributes to tumor cell proliferation in vitro and in vivo and this has been linked to its role in regulating pHi." (PMID 28055960, 2017). "The majority of pre-clinical data for CA9 has involved mixed use of shRNA and various inhibitors with the greatest success being realized in syngeneic mouse tumor models." (PMID 28055960, 2017). "Recent support for importance of HCO3- uptake in tumor cells has strengthened the need to further understand CA9 activity in the tumor microenvironment." (PMID 28055960, 2017). "Here, we have investigated for the first time, the role of CA9 via complete genomic knockout (ko) and compared its impact on tumor cell physiology with the essential pHi regulator Na+/H+ exchanger 1 (NHE1)." (PMID 28055960, 2017). "The expression of the tumor hypoxia marker carbonic anhydrase 9 (CA-IX) was also scored in the TMAs." (PMID 27869162, 2017). "Evidence indicates that the activity of carbonic anhydrase (CA9), which converts carbon dioxide and water to carbonic acid, is strongly induced in hypoxia contributing to low pH of the tumor." (PMID 28045438, 2017).
tumor (continued). "A allele at CA9 rs1048638 impairs miR-34a, a tumor suppressor miRNA in HCC, binding to CA9 3′UTR and desensitizes CA9 mRNA to miR-34a-dependent RNA degradation." (PMID 28667334, 2017). "The mechanism of enhancement is believed to be due to an increase in pH and blockade of the tumor’s ability to adapt to hypoxic conditions perpetuated through simultaneous CA9 and Ref-1/APE1 blockade." (PMID 28825044, 2017). "The median percentage of tumor surface area positive for CA9 and CD31 immunohistochemical staining were 7.8% and 8.1%, respectively." (PMID 27637082, 2016). "1.7% ± 0.6% of tumor cells in Calu-3 tumors were positively stained with CA9, indicating that Calu-3 xenograft tumors are well-oxygenated." (PMID 27020103, 2016). "In these tumors, hypoxia was concentrated at the rim between the tumor and the normal tissue, whereas in the tumors that responded to sunitinib treatment, the entire surface stained for CA9 and thus was hypoxic." (PMID 27509260, 2016). "Immunostaining for glucose transporter 1 (GLUT1) and the hypoxia marker carbonic anhydrase 9 (CAIX) in tumor, normal mammary gland and MINO (precancer) tissue showed differences in expression." (PMID 27630987, 2016). "The immunofluorescence analysis of CA9 protein revealed a significant increase and typical membrane localization in 2D tumor cell cultures exposed to adipocytes, indicating activation of HIF-1α signaling." (PMID 27458427, 2016). "Those experiments deserve special attention due to the reported effects that promoter methylation exerts on expression of hypoxia-controlled genes (e.g., CA9, studied herein) in context of tumor microenvironment." (PMID 27379206, 2016). "In contrast, CA9 staining was rarely seen in Calu-3 xenograft tumor cells, with staining evident only in occasional isolated cells." (PMID 27020103, 2016). "In axitinib-treated and control tumors, CA9 staining was mainly confined to the tumor edges, whereas in the everolimus- and sorafenib-treated tumors, staining was evenly distributed." (PMID 27509260, 2016). "The hypoxia-inducible enzyme CA9, overexpressed in cancer cells, has been proposed as a marker for hypoxic exposure and tumor aggressiveness." (PMID 27379206, 2016). "We have shown that miR-210 is significantly associated with all hypoxia-related markers available for analysis; HIF-1α, CA9, Glut-1, tumour necrosis and expression of a 26-gene head and neck signature." (PMID 27441495, 2016). "The hypoxia-related markers CA-9 and clusterin significantly increased following treatment with cabozantinib, suggesting modulation of tumour hypoxia or the response thereto in the presence of cabozantinib." (PMID 26762579, 2016). "We also found that sCA9 and tumor CA9 levels in late stage of CRC patients were higher than in early stage of CRC patients." (PMID 26447758, 2015). "In the present study, we also observed that the average serum CA9 levels were remarkably increased in CRC patients, which were correlated with tumor tissue CA9 expressions." (PMID 26447758, 2015). "In contrast to tumor tissue CA9 protein analysis, serum CA9 level examination in CRC patients is relatively rare." (PMID 26447758, 2015). "CA9 inhibitor such as sulfonamides is known to block CA9 activation and reduce tumor growth consequently." (PMID 26447758, 2015). "For example, CA9 staining was markedly pronounced in tumours formed by cells precultured in hypoxia." (PMID 25664931, 2015). "Inhibition of CA9 has been shown to slow tumor growth, inhibit metastasis, and decrease tumor stem cells in mice." (PMID 26156831, 2015). "The primary enzymatic function of CA9 is to catalyze the reversible hydration of carbon dioxide to bicarbonate and protons to contribute to acidification of the tumor microenvironment, acting as a “catalytic converter” for the excretion of acid from cells." (PMID 25890268, 2015). "Compared to CA9 specific monoclonal antibody, the CA9 specific small molecule-based probes provided some advantages for tumor imaging." (PMID 26447758, 2015).